IL6 (interleukin 6)
Diseases named in the same sentence as IL6 in open-access papers (continued):
Sharing a sentence is not in itself a finding about the gene and the disease.
lymphopenia (continued). "Consistent with this, lymphopenia correlates strongly with increased serum levels of IL-6, as well as soluble IL-2 receptor and TNF receptor in soft tissue sarcomas." (PMID 22369276, 2012). "THS also elicited a robust inflammatory response, with significant elevations in circulating interleukin-6 and high mobility group box 1 (both: P < 0.001), neutrophilia ( P < 0.001), lymphopenia ( P < 0.001), and increased inflammatory gene expression across a number of tissues." (PMID 41185419, 2025). "Moreover, the excessive secretion of IL-6, D-dimer and lymphopenia produced during the primary COVID-19 infection increases the likelihood of developing post-COVID-19 syndrome." (PMID 39640203, 2025). "Future studies in different models of CAC shall entangle how RK prevents cancer‐induced lymphopenia and reduces circulating IL‐6 concentrations and whether RK exerts its beneficial effects by modulating the abundance of other cachexokines." (PMID 38302863, 2024). "Under lymphopenic conditions, IL-6 may facilitate lymphopenia-induced proliferation of autoreactive T cells, which could contribute to the development of co-morbidities observed in adult CHD patients." (PMID 38393459, 2024). "Laboratory tests revealed high inflammation parameters (PCT, CRP, Il-6), in blood count: lymphopenia and thrombocytopenia, coagulopathy, hyperferritinemia, increased activity of transaminases, high level of troponin and N-terminal pro B-type natriuretic peptide (NT-proBNP) values." (PMID 38543912, 2024). "Accordingly, the beneficial effect of RK on cancer‐induced lymphopenia may partially be mediated by reducing IL‐6 concentrations." (PMID 38302863, 2024). "In contrast, IL-6 and the lymphocytopenia revealed good sensibilities, with lower specificities." (PMID 38793006, 2024). "Hyperinflammation may cause lymphopenia by inducing apoptosis, pyroptosis (both due to prolonged secretion of TNF-α, IL-6 or IL-18), or PANoptosis (due to the synergistic effect of IFNγ and TNF-α)." (PMID 39896810, 2024). "There was significant correlation between lymphopenia and IL-6 gene expression." (PMID 36674654, 2023). "COVID-19 patients with weaker innate immunity, as manifested by lower HLA-II expression level, are more likely to show severe symptoms (~20%), including lymphopenia and cytokine release syndrome, otherwise known as “cytokine storm”, accompanied by elevation of the proinflammatory cytokine IL-6." (PMID 37656752, 2023). "A differential immune trait in DYS patients at ICU admission, with persistent lymphopenia, enriched CM T-cells, and higher IL-6 may suggest distinct inflammatory states or migration patterns in patients that develop cardiac injury." (PMID 36633703, 2023). "Several studies have reported cellular and molecular changes related to immunity include lymphopenia, neutrophilia, inflammatory cytokines, IL‐6, TNF‐α granulocyte colony‐stimulating factor (G‐CSF) and monocyte chemoattractant protein‐1 (MCP1) in severe COVID‐19 patients." (PMID 38156391, 2023). "IL-6, IL-10, TNF, neutrophils, and dendritic cells cause lymphopenia." (PMID 37673862, 2023). "They suggested that IL-6 and Fas-FasL interactions mediated apoptosis could be involved in the development of lymphocytopenia." (PMID 36034704, 2022). "Hazard of death for patients categorized in the high-risk according to IL-6 was 2.27 (1.23 - 4.18), while for combinations of IL-6 + FME + lymphopenia + creatinine and B/T complex ratio + lymphopenia + creatinine increased to 5.12 (2.51 – 10.41) and 3.02 (1.84 - 4.97), respectively." (PMID 35634332, 2022). "The results of the laboratory showed that lymphocytopenia (79.2%), decreased levels of haemoglobin (77.7%), increased levels of interleukin 6, C-reactive protein, serum ferritin, and D-dimer (77.2%, 55.3%, 55.3%, and 25.9%, respectively), and leukocytopenia (25.9%) were more common." (PMID 35128118, 2022).
lymphopenia (continued). "Furthermore, viremia was the most useful biomarker for these outcomes, being superior to IL6, lymphopenia and LDH." (PMID 35783606, 2022). "These works provided homogenous results describing that, upon hospital arrival, the most severe phenotype associated with inflammatory response (e.g., moderate plasma IL-6 elevation) and altered cellular immunity, i.e., decreased monocyte HLA-DR expression (mHLA-DR) and marked lymphopenia." (PMID 33845874, 2021). "IL-6 may provide a common link between hyponatremia and lymphopenia, as IL-6 can lead to lymphopenia and has been shown to be inversely correlated with sodium levels in COVID-19 in an Italian study." (PMID 35095756, 2021). "Thus, although IL-6 can promote the differentiation of Th17 cells and the secretion of IL-17A and IL-22, low levels of IL-17A and IL-22 are more likely due to lymphopenia." (PMID 34692846, 2021). "IL-6 can end the activation of normal T cells, which may be a reason for lymphopenia; robust proinflammatory function; and inducing a variety of acute-phase proteins, such as CRP." (PMID 33602326, 2021). "Low HLA-DR is caused by monocyte hyperactivation, high levels of circulating IL-6, and lymphopenia." (PMID 34199761, 2021). "Lymphopenia and high levels of ferritin and IL-6 have been reported to be predictors of mortality." (PMID 34578460, 2021). "High IL-6 levels and lymphopenia have been proposed as predictors of disease progression." (PMID 33832474, 2021). "In our study, neither IL-6 dosage nor lymphopenia were associated with the risk of hospital-acquired infections." (PMID 34036411, 2021). "Previous studies indicated that IL-6 could suppress normal T cell activation while IL-8 would attract neutrophil granulocytes and T lymphocytes, which might partly explain the lymphopenia." (PMID 33542929, 2021). "In addition, SARS-CoV-2 produces a wide array of laboratory abnormalities, including lymphopenia, elevated c-reactive protein, sedimentation rate, D-dimer, IL-6, and various cytokine elevation." (PMID 33501389, 2020). "Interstitial pneumonia and lymphopenia, driven by high levels of pro-inflammatory cytokines including interleukin 6 (IL-6) and tumor necrosis factor alpha (TNF-α), C-X-C ligand 10 (CXCL10), C-C motif ligand 2 (CCL2) and CCL3, may be seen in severe cases." (PMID 33302366, 2020). "Lymphopenia, elevated C-reactive protein, and elevated interleukin-6 were found upon admission." (PMID 33058760, 2020). "Children with MIS-C often develop severe lymphopenia that may be secondary to increased levels of IL-6, which is known to downregulate lymphopoiesis through effects on hematopoietic stem cells." (PMID 33425823, 2020). "More severe cases, generally defined by hospitalization, intubation, and/or mortality, can also exhibit dyspnea, lymphopenia, and hypoalbuminemia with concomitant increases in the proinflammatory cytokines interleukin 6 (IL-6), tumor necrosis factor alpha (TNF-α), and interleukin 1 beta (IL-1ß)." (PMID 33042114, 2020). "Indeed, neutrophilia and lymphopenia (resulting in an increased neutrophil to lymphocyte ratio), increased systemic interleukin-6 (IL-6) and C-reactive protein (CRP), correlate with incidence of intensive care admission and mortality." (PMID 32943497, 2020). "Directly targeting STING might be more efficient to restrain the delayed cytokine storm and prevent lymphopenia, pneumonitis, and vasculopathy, than blocking only a single cytokine like IL-6." (PMID 33335532, 2020). "Early reports from the Chinese province of Hubei described some predictive biomarkers for the clinical outcome of hospitalised patients, namely lymphopenia and the elevation of D-dimer, ferritin, interleukin 6 (IL-6), troponin and myoglobin, C-reactive protein (CRP) and lactate dehydrogenase (LDH)." (PMID 32605582, 2020). "Lymphopenia and an increase in interleukin-6 (IL-6) were also observed." (PMID 32754041, 2020).
lymphopenia (continued). "In summary, we provide evidence that the suppression of CD4+ T cell activation in response to lymphopenia is determined by a combination of both, clone-specific properties and environmental factors such as the commensal microflora, IL-6 and IFN-γR expression by DCs." (PMID 30792713, 2019). "Hence, the insensitivity of CD4+ T cells to lymphopenia relies on cell-intrinsic properties and a complex interplay between the commensal microflora, IL-6, IFN-γR+ DCs, and T cell-derived IFN-γ." (PMID 30792713, 2019). "It should be kept in mind that the patient group with s-IL6 levels above the cut-off values may proceed to lymphopenia, hypoalbuminemia, advanced stage, B symptoms, poor performance status, thrombocytosis, elevated LDH, and high mortality." (PMID 25805671, 2015). "In addition, due to substantial missingness of CRP data and the absence of IL-6 measurements in our dataset, we were unable to validate the proposed inflammation-related mechanisms underlying hypoalbuminemia and lymphopenia." (PMID 40551734, 2025). "This transition mirrors immunological shifts: CRP production is more robust in older children due to enhanced hepatocyte response to IL-6, while lymphopenia (integrated in CALLY) may be less specific in bacterial/viral co-infections prevalent in this age group." (PMID 41321450, 2025). "While impaired T- and B-cell differentiation, significant lymphopenia, and decreased production of proinflammatory cytokines such as IL-6, TNF, and IL-12 lead to immunodeficiency, active inflammasome formation and necroptosis might be related to the inflammatory component of the disease." (PMID 38676845, 2024). "In relation to laboratory markers, lymphopenia (Z = 2.50; p = 0.012), thrombopenia (Z = 2.40; p = 0.016) and higher levels of serum LDH (Z = 2.89; p = 0.004), C-reactive protein (Z = 2.86; p = 0.004), procalcitonin (Z = 3.58; p < 0.001) and IL-6 (Z = 2.82; p = 0.005) were associated with mortality." (PMID 39023662, 2024). "Therefore, the observed inverse relation between lymphocytes and immature myeloid cells, the positive relation between absolute numbers of IG and IL-6, and the physiopathological basis that explains, in part, the lymphopenia, led us to calculate the Lymphocyte to Immature Granulocyte ratio." (PMID 37205683, 2023). "The interleukin-6 level was estimated using an enzyme-linked immunosorbent assay (ELISA), and serum IL-6 levels were determined for all patients with and without lymphopenia and controlled following the manufacturer's instructions and guidelines (PeproTech, USA)." (PMID 35721343, 2022). "Similarly, SARS-CoV-2 triggers release of IL-6, TNF, IL-10, and PD-1 from alveolar macrophage, which may contribute towards and compound ongoing cytokine storm, causing lymphocytopenia." (PMID 35883618, 2022). "The models revealed distinct favorable phenotypes—particularly patients with IL-6 > 86 pg/mL, lactate dehydrogenase (LDH) >346 U/L, lymphopenia, and fibrinogen ≤ 8.3 g/L." (PMID 41992182, 2026). "Notably, IL-6 ≤ 5.8 was associated with D0 lymphopenia but not severe lymphopenia." (PMID 39810077, 2025). "Pro-inflammatory cytokines (IL-6 and TNF-α) have been shown to suppress TSH secretion and promote lymphopenia, suggesting a potential link between endocrine and immune dysregulation." (PMID 41375681, 2025). "Neutrophilia is driven by cytokines like IL-6 and TNF-α, while lymphopenia results from chronic immune activation and apoptosis." (PMID 40337399, 2025). "These included lymphopenia and elevated inflammatory markers such as C-reactive protein (CRP), lactate dehydrogenase (LDH), ferritin, D-dimer, and interleukin-6 (IL-6)." (PMID 40731812, 2025). "Laboratory tests showed in blood count that leukocytosis, neutrophilia, and lymphopenia high levels of ESR, CRP, ferritin, D-dimers, LDH, and Il-6 increased transaminase activity." (PMID 38543912, 2024).
lymphopenia (continued). "The blood panel of the participants showed leukocytosis, with lymphopenia (characteristics of the COVID-19 infection) and increased inflammatory markers CRP, D-dimer, ferritin, and IL-6." (PMID 38313184, 2023). "These patients also showed variation of some of the other haematological parameters tested at admission: increased IL-6, IL-10 and CRP, leucocytosis, neutrophilia, and lymphopenia." (PMID 37215142, 2023). "APLA-positive and APLA-negative patients who had lymphocytopenia presented higher levels of LDH activity, D-dimer, ferritin, and CRP at admission and 48 h later, and IL-6 was higher on admission than the reference values." (PMID 37626797, 2023). "The blood count showed leukocytosis, lymphopenia (characteristics of the COVID-19 infection), and increased inflammatory markers, namely CRP, D-dimer, ferritin, and IL-6." (PMID 38313184, 2023). "Some studies suggest associations between lower Ct values on admission samples and disease severity markers, including elevated levels of IL-6, LDH, CRP, lymphopenia and an elevated neutrophil/lymphocyte ratio." (PMID 37213664, 2023). "Similarities included resolution of lymphopenia and neutrophilia and a rapid decrease in the serum concentrations of CRP, TNF-α, IL-6, IFN-γ, IL-10, TNFR-1, and IP-10 following treatment with Allocetra-OTS." (PMID 37600829, 2023). "In general, it stands out that the majority of patients had lymphopenia, mild neutrophilia, as well as elevated C-reactive protein (CRP), ferritin, lactate dehydrogenase (LDH), fibrinogen and interleukin-6 (IL-6)." (PMID 37892366, 2023). "Other identified risk factors were age 6–12 years and especially 13–20 years, non-Hispanic Black ethnicity, shortness of breath, abdominal pain, thrombocytopenia, lymphocytopenia, and increased levels of CRP, troponin, ferritin, D-dimers or IL-6." (PMID 37046304, 2023). "Although IL-6 signalling components served as independent predictors of death within 30 days, the models including B/T complex ratio and IL-6 + FME with lymphopenia + creatinine showed the most significant divergences in the overall survival outcome." (PMID 35634332, 2022). "The resulting receiver operating characteristic (ROC) curves yielded areas under the curve (AUC), which, in male patients, were > 0.7 (p < 0.0001) for IL-6, LDH, and neutrophilia, and < 0.23 for lymphopenia and testosterone." (PMID 35351135, 2022). "Significant differences were also found in laboratory examinations that showed in patients from Group 2 a minor degree of lymphopenia and reduced levels of LDH and inflammatory parameters, including ferritin and IL-6 levels." (PMID 36078552, 2022). "Next, there is older evidence from other clinical scenarios suggesting that multiple cytokines (IL-1, IL-6, TNF-α) are involved in generating lymphopenia by inducing apoptosis." (PMID 36676656, 2022). "The women who required admission to ICU and oxygen therapy, or mechanical ventilation, presented with leukopenia and lymphopenia, elevated levels of CRP, D-dimer, lactate dehydrogenase (LDH) and interleukin 6 (IL-6)." (PMID 36430023, 2022). "At the time of TOC administration all patients had a hyperinflammatory state characterized by increased levels of IL-6, CRP, ferritin, LDH and/or D-dimers, as well as lymphopenia." (PMID 35268338, 2022). "Steroid‐induced lymphopenia occurs via inhibition of T‐cell activation by inhibition of IL‐2, IL3, IL‐4, and IL‐6,43 and suppression of dendritic cell maturation and function." (PMID 35478442, 2022). "Our comparative analysis of biochemical and hematological parameters has revealed that both sexes share markers with significant predictive power of disease outcome, including IL-6, LDH, D-dimer, lymphopenia, and neutrophilia." (PMID 35351135, 2022). "The severe group exhibited lymphopenia, especially in T-cell cytopenia, and hyper-cytokines, notably increased TNF-α and IL-6." (PMID 35573725, 2022).
lymphopenia (continued). "The most laboratory abnormalities found in patients were lymphopenia, increased levels of C-reactive protein/erythrocyte sedimentation rate (CRP/ESR), increased lactate dehydrogenase (LDH) level, high IL-6 level, high ferritin and increased d-dimer level." (PMID 34952570, 2021). "Lymphopenia, neutrophilia, and high levels of AST, BUN, CK, LDH, CTnI, ProBNP, Fbg, d-dimer, IL-6, CRP, procalcitonin, and serum ferritin were all significantly correlated with disease aggravation." (PMID 33850192, 2021). "Cytokine release syndrome (CRS) manifests many abnormalities such as lymphopenia, high levels of C-reactive protein (CRP), high Ferritin, high D-dimers, high lactate dehydrogenase (LDH) and interleukin-6 (IL-6)." (PMID 33411791, 2021). "SARS-CoV-2 patients showed lymphopenia, along with increased inflammation markers including ferritin, CRP and IL-6 levels." (PMID 35126186, 2021). "The most frequent laboratory findings are an increase in inflammatory indices (CRP, procalcitonin, ferritin, ERS, IL-6), cardiac markers (BNP, troponin), and D-dimer levels, leukocytosis (with lymphopenia), and reduced albumin levels." (PMID 34422717, 2021). "T cells reduction in the blood is also a contribution of mechanisms such as inflammatory cytokine milieu, which is why lymphopenia has a correlation with TNF-α, IL-6, and IL-10." (PMID 33716737, 2021). "In terms of laboratory findings, lymphopenia and elevation of inflammatory biomarkers (CRP, ESR, IL-6), and higher levels of D-dimer and lactic acid were associated with severe patients." (PMID 34344306, 2021). "In contrast to Western literature, our cancer patients demonstrated significant lymphopenia and elevated inflammatory markers (CRP and IL‐6) versus non‐cancer patients." (PMID 34786866, 2021). "What is particular to this stage is the increase in inflammatory markers (CRP, LDH, IL-6, D-dimers, ferritin, prothrombin, troponin, NT pro BNP), as well as marked lymphopenia." (PMID 34201473, 2021). "Fewer platelets, CD3 or CD4 counts, lower complement C3 level, lymphopenia, and elevated APTT, IL-6 or IL-10 also were related to the progression from oneset to death (all P < 0.05)." (PMID 32903644, 2020). "On 10 February 2020 (day 1 after admission), blood biochemical examination showed eosinopenia, lymphopenia, elevated HSCRP and increased IL-6 concentration." (PMID 33208927, 2020). "The immunological profile is characterized by the reduction of CD4+ and CD8+ T-lymphocytes (lymphopenia), decreased level of CD4+cell expression of INF-γ and increased cytokines Interleukin-6 (IL6), IL-10 and tumor necrosis factor-alpha (TNFα)." (PMID 32974295, 2020). "An important finding of our study was the presence of lymphopenia and elevated inflammatory markers including CRP, LDH, Ferritin, D-dimer, and IL-6 levels in almost all patients who developed spontaneous pneumothorax." (PMID 32938445, 2020). "Patients with severe infections have shown to have high inflammatory markers such as IL-6, CRP, D dimer, LDH and lymphopenia." (PMID 32664810, 2020). "The laboratory abnormalities observed in this study were leucopenia, lymphopenia, elevated D-dimer, ESR, IL-6, serum ferritin, CRP, and LAC, which were related to sustained inflammatory response." (PMID 32792492, 2020). "Age, lymphopenia, leucocytosis, and elevated ALT, lactate dehydrogenase, high-sensitivity cardiac troponin I, creatine kinase, D-dimer, serum ferritin, IL-6, prothrombin time, creatinine, and procalcitonin were also associated with death." (PMID 33363221, 2020). "Moreover, lymphopenia and thrombocytopenia were observed at the later stages of disease together with sharp increases in plasma levels of proinflammatory cytokines (IL-1β, IL-18, IL-6, and IFNα) and chemokines (I-TAC, MCP-1, and eotaxin), also characteristic of EHF." (PMID 28852031, 2017).